CCL2 (C-C motif chemokine ligand 2)
Diseases named in the same sentence as CCL2 in open-access papers (continued):
Sharing a sentence is not in itself a finding about the gene and the disease.
cancer (continued). "For example, cisplatin triggers the expression of multiple cytokines including IL-6, CCL2, CCL5, CXCL8, BFGF, G-CSF, and VEGF in cancer cells or stromal cells of TME." (PMID 35784460, 2022). "Accordingly, the cancer cells play a key role in neutrophil infiltration into TME by producing different signals including chemokines (e.g., IL-8, CCL2, CXCL6) and cytokines (e.g., IL-1β, IL-6, TNFα)." (PMID 36330498, 2022). "The chemokine CCL2 and its receptor CCR2 are known to regulate macrophage recruitment during inflammation and cancer progression." (PMID 35405500, 2022). "For instance, CC-chemokine ligand 2 (CCL2, or MCP1), well-known as an inflammatory chemokine, has been shown to promote the progression of many cancers, including PCa." (PMID 36077602, 2022). "Accordingly, downregulation of CCL2 expression enhanced CD8+ T cell-mediated antitumor immunity, which mitigates cancer immunosuppression and overcomes PD-1 immunotherapy resistance by inhibiting TAM and G-MDSC infiltration." (PMID 36077785, 2022). "CCL2, a crucial chemokine in TME, functions mainly through binding to its receptor CCR2 and recruit macrophage and monocyte, which promotes cancer progression and metastasis." (PMID 35978854, 2022). "CCR2 is the receptor for CCL2/MCP-1 (Monocyte Chemotactic Protein 1), and their interaction is the main driver of the recruitment of monocytes to tissues, including cancer tissues." (PMID 35565443, 2022). "Potential targets of statins for cancer treatment identified by LIGHTHOUSE included STAT3, CCND1, AKT1, and CCL2." (PMID 36246574, 2022). "To investigate the relevance of our findings to KRAS-mutant human cancers, we analyzed the average expression of KRAS, CCL2, and IL1B genes in public data (GSE43458) from the BATTLE trial." (PMID 35327394, 2022). "CCL2, CRIM1, COL1A1, 6A1, 6A2 participate in cell migration, invasion, or EMT and ABCG2, ALDH1A1, NES are cancer stem‐cell markers." (PMID 36305167, 2022). "Due to the contribution of the CCL2/CCR2 and CXCL1/CXCR2 axes to the pathology of various cancers, there have been attempts to develop CCR2 and CXCR2 antagonists, anticipating therapeutic benefits from CCR2 and CXCR2 inhibition." (PMID 36403057, 2022). "The importance of the CCL2/CCR2 and CXCL8/CXCR2 axes in various cancers has led to the development of several small-molecule inhibitors that target the two axes." (PMID 36403057, 2022). "In recent years, the role of the chemokine CCL2 and its major receptor CCR2 in cancer pathogenesis has received special attention, and elevated levels of CCL2 have been associated with increased growth and progression of a variety of cancers." (PMID 35957694, 2022). "To this aim, we measured CCL2, CCL3, CCL4, and CCL5 by CBA in TCM from different cancer types or in cultures of BM cells stimulated with the same TCMs or with recombinant cytokines involved in MDSC differentiation." (PMID 35064009, 2022). "Along with CCL7, which is downregulated 2-fold in our hPARG-expressing cells, CCL2 activates the CCR2 receptor (C-C Motif Chemokine Receptor Type 2) pathway, which expression in cancer cells have been demonstrated to promote immune suppression." (PMID 35585513, 2022). "IL‐34, M‐CSF and CCL2 were at first listed as factors related to macrophage chemotaxis, and their expression in HMDM and cancer cell lines were tested by real‐time PCR." (PMID 35132816, 2022). "PLG regulates macrophage invasion, MMP proteins, or CCL2/CCR2 axis and is involved in cancer cell proliferation, migration, growth, and metastasis." (PMID 34861103, 2022). "In cancer and inflammatory diseases, the major inflammasome is TNF-α, which activates the NF-κB pathway, whereas the minor inflammasomes are IL-1β, CCL2, and CCL5." (PMID 36139553, 2022). "After performing the non-parametric U Mann–Whitney test comparing the concentrations obtained in both groups, we observed that the levels of CCL2, CCL4, CEA, and CRP in the entire cancer group were significantly higher (in all cases p < 0.05)." (PMID 35407400, 2022).
cancer (continued). "Some of these factors were exclusive to CAFs (mainly CXCL10 and CXCL12), others to cancer cells (mainly CXCL7 and CCL20), and some factors, such as CCL2, were common to both cell types." (PMID 35192545, 2022). "The chemokine CCL2 is elevated in HCC and is connected with malignant activities and poor prognosis, playing an essential role in promoting cancer progression by activating M2 macrophages." (PMID 36238299, 2022). "In some solid tumors, an increasing number of studies have shown that CCL2, CCL17, and CCL22 with CCR4 expression induced cancer cells migration, EMT, and metastasis in some solid tumors." (PMID 35177591, 2022). "Interleukin (IL6) and C‐C motif chemokine ligand 2 (CCL2), two cytokines secreted by CAF, play important role in cancer cell migration." (PMID 35978854, 2022). "Glial cells, such as astrocytes, can also induce cancer cell transmigration through the BBB, notably by the secretion of CCL2 as demonstrated in a 3D in vitro human BBB model." (PMID 35884845, 2022). "The CCL2/CCR2 and CXCL8/CXCR2 axes play an essential role in the malignant progression of tumors and act as novel targets for cancer treatment." (PMID 36403057, 2022). "The CCL2/CCR2 axis has been proposed as a potential target for decreasing MDSCs recruitment and improving cancer treatment." (PMID 34874922, 2022). "Along the paclitaxel-mediated ICD, the cancer cell autonomous TLR4 signaling is essential to the release of DAMPs, which led, in an autocrine manner, to the activation of the NF-κB-mediated CCL2 transcription, together with CXCL10." (PMID 36429101, 2022). "Our experimental approach exploits the paracrine up-regulation of CCL2, CCL5, IL-1β, and IL-6 in ADMSC in response to TNBC cells secretome, confirming and complementing prior co-culture approaches mixing cancer cells and adipocytes." (PMID 35268073, 2022). "Schematically, cancer cells secrete cytokines and chemokines, such as TGF-β and CCL2, involved in the recruitment and activation of CAF and mononuclear inflammatory cells, as well as the tumorigenic transformation of macrophages." (PMID 34112253, 2021). "This is evident with the demonstration that growth factors such as CCL2 and hepatocyte growth factor (HGF) induced CSC renewal and stemness of cancer cells in both breast and hepatocellular carcinoma." (PMID 34122412, 2021). "In TME, CCR2 interacts with CCL2 to mediate chemotaxis of monocytes and TAMs, which consequently contributes to the shaping of TME and promotes cancer progression and metastasis." (PMID 34251980, 2021). "The secretion and production of chemokines such as CCL2, CXCR1/2, CXCL12, CXCR4, and CXCL8 play critical roles in cancer development and subsequent metastasis." (PMID 34530822, 2021). "The expression levels of CCL2 and CCR2 can be regarded as a predictor of poor prognosis in patients with cancer." (PMID 34464477, 2021). "PIPKI γ is highly expressed in the cancer tissues of CRC patients with poor prognosis, increases CCL2 expression through Akt-STAT3 signal activation, and recruits TAMs to the TME." (PMID 34445235, 2021). "The function of ATF4 in regulating cancer progression was also found to be related to PERK and CCL2 10,15." (PMID 33628101, 2021). "To investigate their sub-exosomal localization, we added recombinant human or mouse CCL2 and IL-6, both cytokines present in both plasma exosome isolates and TIF, to two human and two murine cancer cell line-derived exosomes." (PMID 34112803, 2021). "We selected the eleven cytokines that were significantly increased in cancer (GMCSF, IL-6, IL-1β, Rantes/CCL5, MIP1α, MIP1β, TNFα, MCP1/CCL2, IL-8, IL-12p40, IL10) and selected all the positive Pearson's correlations with r > 0.8 and significance of p < 0.01." (PMID 35048057, 2021). "Both CCR2 inhibitors and anti-CCL2 monoclonal antibodies have been used in pre-clinical murine models to disrupt this CCL2/CCR2 interaction, showing efficacy both on their own and in combination with other anti-cancer therapies." (PMID 34209703, 2021).
cancer (continued). "Cancer cell motility can be influenced by the CAF expression of chemotactic chemokines such as stromal derived factor (SDF-1 or CXCL12), and C-C Motif Chemokine Ligand 2 (CCL2)." (PMID 34071280, 2021). "We focused on CCL2 and VEGF-A as previous research suggested their molecular connection to CHI3L1 in the context of different cancers." (PMID 33920100, 2021). "It is important to note that even when cancer cells are resistant to TRAIL, exposure activates the secretion of the immune-suppressive cytokines, IL8, CXCL1, CXCL5, and CCL2 in a FADD-dependent way." (PMID 34371753, 2021). "The axis of chemokine CCL-2 and its receptor CCR2 are identified as the elements in cancer–nerve crosstalk, forming a tumor microenvironment that facilitates the PNI." (PMID 34441243, 2021). "Statins disrupt communication between cancer cells and mesenchymal stromal cells (MSC) by inhibiting CCL3 secreted by cancer cells and IL-6 and CCL2 produced by MSC." (PMID 34858839, 2021). "Paget postulated that various cytokines secreted from cancer cells, including CCL2, CCL5, and interleukin-6, and a specific microenvironment communicates to attract cancer cells toward specific organs." (PMID 33806911, 2021). "Inhibition of CCL2 is important because CCL2 produced by cancer cells recruits macrophages to the TME and directly increases the metastatic potential of cancer cells." (PMID 35008577, 2021). "CCL2, another chemokine downregulated by USP12, also contributes to the recruitment and polarization of cancer-promoting myeloid cells." (PMID 34381028, 2021). "Therapeutic strategies targeting the CCL2‐ CCR2 axis have also shown promising effects, enriching our approaches for fighting against cancer." (PMID 34464477, 2021). "Intriguingly, bioinformatic analysis revealed that CCL2 and LDHA were both strongly increased in M-BCSCs population (CD44+ cancer cells) compared with the bulk cancer cells according to the GSE115302 data set." (PMID 34178639, 2021). "CCL2/CCR2 signaling played a key role in the stimulation and sustainment of cancer cell proliferation, invasion migration, and metastasis, and induction of deleterious inflammation and angiogenesis." (PMID 34251980, 2021). "First, in 9502 patients with 33 different types of human cancer, the subset of tumors with MYC and TWIST1 predicts poor survival, CCL2/IL13 expression and TAM infiltration." (PMID 31933479, 2020). "The chemokine CCL2 and its main receptor CCR2 have been receiving particular interest on their roles in cancer pathogenesis." (PMID 32471499, 2020). "CCL2 and its receptor CCR2 were reported to play crucial roles in cancer metastasis, accelerate cancer cell growth, and promote their colonization at metastasis sites." (PMID 32064233, 2020). "A large body of evidence has demonstrated that several chemokines, including CCL2, CCL5, and CSF-1, are released under hypoxic conditions to promote the migration of TAMs into the nutrient-deprived region of cancer." (PMID 32283687, 2020). "We observed higher levels of Il-1β, Ccl2, Ccl3, Il23, and iNos mRNA in the differentiated MPRO cells cultured in the supernatant of cancer cells compared with MPRO cells cultured in SF media." (PMID 33049964, 2020). "In many tumors, TAM is recruited into microenvironments by CCL2, CSF-1, IL-10, TGF-β, etc. secreted from cancer cells." (PMID 31963413, 2020). "CCL2, CXCL10, and CX3CL1/CX3CR1 can serve as both favorable and unfavorable prognostic factors for cancers depending on cancer types." (PMID 31991604, 2020). "Blockade of CCL2/CCR2 axis reduced the frequency of immunosuppressive myeloid cells and showed anti-tumoral efficacies in different preclinical cancer models." (PMID 32823961, 2020). "Both MYC and Twist1 demonstrated binding at multiple sites in the promoter regions of CCL2 and IL13 in the ChIP-seq data from several different cancer cell lines." (PMID 31933479, 2020).
cancer (continued). "Further, in 33 human cancers (n = 9502) MYC and TWIST1 predict poor survival (p=4.3×10−10), CCL2/IL13 expression (p<10−109) and TAM infiltration (p<10−96)." (PMID 31933479, 2020). "CCL2, in turn, regulates CCR2+ macrophage signaling and induces, for example, secretion of CCL3 and consequent extravasation of cancer cells." (PMID 32655574, 2020). "This revealed that patients that had higher levels of MYC and TWIST1 proteins in their tumors also had increased levels of CCL2 and IL13, more activated macrophages and were less likely to recover from their cancer." (PMID 31933479, 2020). "Further, combined MYC and TWIST1 expression correlated strongly with CCL2 and IL13 in the pan-cancer cohort (p=1.4×10−109)." (PMID 31933479, 2020). "While CCL2, CXCL10, and CX3CL1/CX3CR1 can serve as favorable or unfavorable prognostic factors depending on the cancer types, CCL14 and XCL1 possess good prognostic value." (PMID 31991604, 2020). "FOXQ1 is an established modulator of Twist1 expression and a regulator of cancer invasion and metastasis in CRC, and the role of Twist1-induced CCL2 in angiogenesis has been previously demonstrated." (PMID 33330033, 2020). "(a) Disease-free survival in pan-cancer TCGA cohort of 9502 patients from 33 cancers stratified by median MYC+TWIST1 expression (first KM curve) and median MYC+TWIST1+ CCL2+IL13 (second KM curve)." (PMID 31933479, 2020). "These macrophages show the expression of the M2 polarization marker CD206, as well as the expression of cytokines that are important in the progression of cancer: IL-10, CXCL8/IL-8 and CCL2/MCP-1." (PMID 33114763, 2020). "CCL2 and CCL3 are secreted by M1 macrophages which promoted a strong immune response to kill the cancer cells." (PMID 32256661, 2020). "After cocultivation with HeLa and ME-180 cells, the expression of CCL2 in SCs and its receptor CCR2 on the membrane of cancer cells both increased." (PMID 32064233, 2020). "After traversing BBB, cancer cells secrete various cytokines, chemokines, and mediators, particularly IL-1β, TNF-α, IFN-γ, CCL2, CXCL8, and COX2." (PMID 31900168, 2020). "Anti-cancer properties have also been shown in the clinical trials of carlumab (CNTO888), a monoclonal antibody against CCL2, in patients with solid tumors." (PMID 33182504, 2020). "CCL2 induces cancer cell migration and contributes to the early stages of metastasis by interacting with CCR2 expressed on cancer cells." (PMID 33297571, 2020). "The discussed group of CC chemokines (CCL2, CCL7, CCL8, and CCL13) have numerous pro-cancer functions, which outweigh their anti-cancer properties." (PMID 33182504, 2020). "Homing of MSCs to tumor sites involves a number of cytokines and chemokines, including CCL2, CCL5, CXCL12, secreted by cancer cells." (PMID 32957515, 2020). "Our experiments demonstrate that cancer cells stimulate the proliferation of fibroblasts and educate them to express pro-angiogenic proteins CXCL8 and CCL2." (PMID 32214219, 2020). "CCL2 and CLL7 have also been well researched as therapeutic targets in cancer therapy due to their significant function in tumors." (PMID 33182504, 2020). "Bioinformatic analyses, performed to assess the role of 41 cytokines after RT exposure and their network interactions, suggested TGF-β, MIF, CCL2, CXCL5, CXCL8 and CXCL12 as master regulators of cancer immune escape in RMS tumors." (PMID 32854690, 2020). "We identify carcinoma-educated fibroblasts as the source of angiogenesis via secretions of CXCL8 (aka IL-8) and CCL2 (aka MCP-1)." (PMID 32214219, 2020). "Further in vitro and in vivo clarifications are required to understand the targeting mechanism of the CCL2/CCR2 pathway using CR and its nano-combination with AV in cancer therapy." (PMID 31350989, 2019).
cancer (continued). "The six main genes are involved in the cancer and inflammatory processes (YWHAZ, CCL2 and SMPD2) and lipid droplet formation and metabolism (CIDEC, VLDLR and FASN) and significantly increased in NASH patients compared to control or NAFL groups." (PMID 31717414, 2019). "C-C motif chemokine ligand 2 (CCL2), also known as monocyte chemotactic protein-1 (MCP-1), is expressed in most human cancers, and plays a key role in the recruitment of macrophages and MDSCs." (PMID 31823764, 2019). "Many other cancer-related genes showed up differentially expressed in PDAC, including MUC2, MUC5B, MUC13, ALDH3A1, CDCA7, and CCL2." (PMID 31379917, 2019). "Encouragingly, many studies correlating with the effects of CCL2, CCL11, and CCL21 on anti-cancer properties focus on their relationships with T cell functions." (PMID 31754081, 2019). "On the front of cancer cells, both TMZ-R and TMZ-S cells showed a significant increase in the M2 cytokines mRNA level of IL-10, IL-4, IL-13 and CCL2 as compared to their parental counterparts." (PMID 31462285, 2019). "Targeting chemokine interactions and subsequent recruitment of macrophages within tumors, including the CCL2/CCR2 or CXCL12/CXCR4/7 chemokine-chemokine receptor axes, have shown great potential for cancer therapies in various mouse models of cancer metastasis." (PMID 30832375, 2019). "Many chemokines, including CXCL1, CCL2, CCL20, CCL4, CCL5, and XCL1, which are produced by both cancer and immune cells, drive BDCA3+ cDC1 recruitment into TME with the potential to induce local cytotoxic T cell function." (PMID 31484464, 2019). "For instance, tumors can early on secrete the colony-stimulating factor 1 (CSF-1 or M-CSF) that expands the pool of macrophages towards the cancer supporting TAM phenotype and later on the chemokine (C-C motif) ligand 2 (CCL2) that attracts monocytes." (PMID 30832375, 2019). "For example, peri-tumor tissue-sourced fibroblasts secrete various cytokines, including IL-6, CXCL1, CCL2, SCGF-β, CXCL8 and HGF, to recruit cancer stem cells, maintain cancer stemness and promote intrahepatic metastasis of HCC." (PMID 30999932, 2019). "Proteomic analysis of the content of these exosomes identified several established cancer- related proteins (i.e., IL-6, IL-8, ICAM-1, CCl2, and OSM)." (PMID 31803630, 2019). "CCL2 and CCR2 are currently therapeutic targets of interest for anti-cancer treatment and inflammatory diseases." (PMID 31208996, 2019). "Molecular method was based on the analysis of selected genes expression related to hypoxia (HIF1A, ANGPTL4, TGFB1, VEGFA, ERBB3, CA9) or specific for inflammation in hypoxic sites (CCL2, CCL5) at various time points after CT26 cancer cells inoculation." (PMID 30412628, 2018). "Remarkably, IL-6, IL-10, CXCR4, and CCL2 mRNA, which are all STAT3 target genes involved in cancer progression, were increased in macrophages exposed to exosomes." (PMID 29867925, 2018). "MCP-1, also known as CCL2, is a chemotactic factor that plays important roles in recruitment and activation of monocytes during acute inflammation and cancer development." (PMID 29507684, 2018). "Our work shows that IL-1β derived from inflammatory UC-MSCs induces the production of downstream cytokines CCL2, CXCL1, IL-6, and IL-8 in an autocrine manner, which promotes stem cell-like characteristics of cocultured cancer cells." (PMID 29670904, 2018). "It is notable that CCR2, which binds CCL2, as well as CCL7, CCL8 and CCL12, play a controversial role in cancer metastasis." (PMID 30591657, 2018). "There is clear evidence that carcinomas, such as BC, PC, lung, and OSCC often utilize both CCL2 and IL-8 to condition the bone microenvironment and promote OBD." (PMID 29930538, 2018). "Increasing evidence points to the vital effects of CCL2/CCR2 on the proliferative and metastatic properties of cancer cells." (PMID 28424406, 2017).